INS (insulin)
Diseases named in the same sentence as INS in open-access papers (continued):
Sharing a sentence is not in itself a finding about the gene and the disease.
diabetes (continued). "This is in line with the findings of a large-scale study from the United States, which investigated the glucose profile of healthy adults and those with prediabetes and non-insulin-treated type 2 diabetes mellitus (n = 665), who all used CGM in combination with a smartphone-based app." (PMID 35271177, 2022). "Her father, affected by diabetes, was treated with basal insulin and metformin." (PMID 36294752, 2022). "The current study also showed those patients with diabetes who were treated with more than 30 IU of an intermediate acting insulin regimen (NPH) had a higher threat of accelerating the development of doubling of the serum creatinine level, as computed from the initial scores." (PMID 36095019, 2022). "GWAS studies have also found multiple non-MHC loci, such as the insulin (INS) loci associated with increased diabetes risk." (PMID 36359215, 2022). "This MNs patch, with a “cake-like”, two-layer structure, displayed acute and sustained self-regulated insulin delivery with significantly improved mechanical strength and skin insertion efficiency, which suggests its potential for diabetes management applications." (PMID 35200456, 2022). "Poor glucose metabolism leads to diabetes, a metabolic disorder of carbohydrate metabolism characterized by high blood glucose levels resulting from insufficient insulin production or an ineffective response of cells to insulin." (PMID 35326203, 2022). "Moreover, a study in the Philippines revealed that patients with diabetes who had been on insulin for a longer period were less likely to dispose of sharps correctly than those who had been on insulin for a shorter period." (PMID 36568796, 2022). "We then investigated whether the behavioral and molecular changes secondary to hyperglycemia were reversed by insulin treatment in an attempt to identify potential novel therapeutic targets for regulating depressive symptoms in patients with diabetes." (PMID 36552776, 2022). "Type 2 diabetes mellitus is characterized by both insulin resistance and beta-cell dysfunction." (PMID 35658859, 2022). "Dedifferentiation of β-cells, characterized by the loss of expression of key β-cell maturation marker genes with an accompanying reduction in insulin secretion, has been observed in mouse models of type 1 (T1D) and type 2 (T2D) diabetes, as well as in individuals with diabetes." (PMID 35399953, 2022). "Diabetes is a chronic disease that occurs when a patient’s pancreas is no longer capable of producing insulin or the patient’s body is unable to fully utilize the insulin it produces, leaving the body incapable of regulating blood glucose levels." (PMID 35746236, 2022). "Some patients with diabetes may need insulin for the rest of their life–some patients with opioid use disorder may need Suboxone for the rest of their life." (PMID 36386988, 2022). "The identification of glucose uptake mediators overcoming leptin and insulin resistance could provide new strategies for the treatment of the major form of type 2 diabetes mellitus." (PMID 35159237, 2022). "Diabetes technology tools including mobile communication technology and computerized insulin administration devices have shown to be promising in improving glycemic control and adherence to insulin therapy." (PMID 35758838, 2022). "If so, this might come to be seen as a landmark achievement, akin to the first use of insulin injection for treatment of diabetes in a person in 1922." (PMID 35104802, 2022). "Owing to the bioactive peptide and hormone-like proteins involved in CM, the insulin dose required for patients with diabetes could be reduced by the regular long-duration administration of CM." (PMID 35334901, 2022). "As fetal growth is heavily regulated by insulin, BW may be acting as a mediator of PW, obscuring any direct relationship between parental diabetes and offspring PW." (PMID 35951032, 2022).
diabetes (continued). "The destruction of β-cells of the pancreas leads to either insulin shortage or the complete absence of insulin, which in turn causes diabetes Mellitus." (PMID 35723344, 2022). "Moreover, the efficacy of mβCD complexed with insulin is being evaluated in preclinical diabetes models." (PMID 35250626, 2022). "Hence, we aimed to assess the association of hepatic steatosis and fibrosis with different measures of insulin sensitivity in patients with severe obesity and type 2 diabetes mellitus (T2DM)." (PMID 36336684, 2022). "The mechanism by which alloxan induces diabetes is that it selectively inhibits glucose-induced insulin production via a specific hexokinase inhibition that triggers a condition similar to T2DM via its capacity to induce ROS, resulting in pancreatic β-cell toxicity." (PMID 35190649, 2022). "Presently, oral drugs and insulin injections are commonly used to treat diabetes." (PMID 36743935, 2022). "However, this compensation cannot be sustained over time, leading to the attenuation of insulin secretion and β-cell mass reduction, which ultimately induces diabetes." (PMID 35829914, 2022). "This suggests that high insulin resistance in the nondiabetic stage contributes to relative insulin-deficient T2D and different diabetes phenotypes." (PMID 35927727, 2022). "As diabetes and its consequences are predominantly a result of excessive glucose levels in the bloodstream, a therapy that reduces glucose levels and improves insulin sensitivity while also affecting the pathophysiological pathways implicated in DR would be most useful." (PMID 35234250, 2022). "Other factors such as the mother’s age, BMI, triceps skin-fold thickness, plasma glucose concentration at 2 h in an oral glucose tolerance test, 2 h serum insulin level, and diabetes degree function were particularly effective in predicting gestational diabetes." (PMID 36360505, 2022). "Third, the mean BG could be influenced by a variety of factors such as diabetes, inflammation, and insulin, which might have biased the results." (PMID 35983431, 2022). "Subgroup analysis was performed on duration of insulin and type of diabetes." (PMID 35123455, 2022). "The association between weight change and the risk of any-fracture was explored, using subgroup analyses, after stratification by age, BMI, sex, diabetes duration, presence of proteinuria, history of hypertension, number of oral hypoglycemic agents, and insulin use." (PMID 35966851, 2022). "On the other hand, minimal models such as those developed for assessing insulin sensitivity and beta cell function are particularly useful in highlighting the contribution of specific impairments to the pathophysiology of diabetes and are more easily validated with data." (PMID 36148302, 2022). "INS mutation was found in a girl that was diagnosed with diabetes at 21 months, probably with DKA (there was no precise clinical information)." (PMID 35769090, 2022). "The most recent Meta-Analyses of Glucose and Insulin-related Traits Consortium (MAGIC) included >280,000 individuals of diverse ancestry without diabetes, and reported associations of variants with glucose, insulin, and HbA1c." (PMID 35956377, 2022). "When NOD mice are exposed to beta-cell stressors that mimic the compensatory insulin over-production observed in T2D, this beta-cell fragility is sufficient to tip the mice into overt diabetes, while the same stressors remain sub-clinical in mice with robust beta-cells." (PMID 36291702, 2022). "In particular, the insulin signaling pathway has implications for the pathogenesis of diabetes." (PMID 36532503, 2022). "In the remaining domains, other questions where there was not a statistical improvement in confidence were areas where providers had started Project ECHO Diabetes with high confidence (for example, demonstrating empathy towards patients living with insulin requiring diabetes)." (PMID 36589850, 2022).
diabetes (continued). "Therefore, evaluation of residual insulin secretion during the course of type 2 diabetes is important when choosing between insulin therapy and other treatments, as diabetes is a lifelong condition." (PMID 35229479, 2022). "However, rodent models of diabetics showed that Rimonabant and Ibipinabant had beneficiary effects on pancreatic islets for regulating blood glucose levels and insulin secretion." (PMID 36159331, 2022). "Diabetes in these lean individuals was more common in men, and predominantly associated with reduced pancreatic secretory function rather than insulin resistance." (PMID 35138411, 2022). "Furthermore, apelin participates in the pathology of diabetes by playing a pivotal role in increasing glucose uptake and insulin sensitivity." (PMID 35663309, 2022). "These early success stories of precise genetic diagnosis and the transformation of treatment from insulin injection to oral drugs have encouraged the scientific community in identifying patients with possible monogenic diabetes and understand the genotype-phenotype correlation." (PMID 35453810, 2022). "Early diabetes onset and a higher dose of exogenous insulin treatment are possible explanations." (PMID 35813369, 2022). "Many participants were adept at self-exempting from the information conveyed by most labels, even those perceived as highly aversive, for example, those stimulating thoughts of insulin injection (diabetes label) or requiring high physical effort (exercise equivalent)." (PMID 35733102, 2022). "Diabetes is a severe, long-term disease that occurs when the pancreas fails to produce enough insulin (a hormone that regulates blood sugar, or glucose), or when the body is unable to use the insulin that is produced." (PMID 35795845, 2022). "Diabetes mellitus is a disease associated with abnormally high levels of blood glucose due to a lack of insulin." (PMID 36099285, 2022). "Second, we aimed to study whether insulin therapy could rescue the effect of STZ-induced diabetes on Cyp2r1 expression." (PMID 35524739, 2022). "The large number of drugs prescribed to patients with hypertension and diabetes mellitus can be attributed to beta-blockers, ACE inhibitors, hypolipidemic agents, calcium channel blockers, insulin, and anticoagulants to decrease the risk of various complications." (PMID 35208508, 2022). "Flavonoids’ potential to alter the insulin signaling pathway in typical target tissues such as muscle, liver and adipose tissue has been shown in abundant scientific studies to help prevent or alleviate insulin resistance in diabetics." (PMID 35335923, 2022). "The most abundant GPCR ligand mRNA in adipose tissue isolated from lean mice was Agt, but while islets express AT1 receptors and exogenous angiotensin stimulates insulin secretion, the systemic hypertensive effects of angiotensin preclude its use therapeutically in diabetes." (PMID 36245259, 2022). "The association between CNTF levels and obesity with or without diabetes was confirmed even when the multiple regression analysis was adjusted for fasting insulin and the interaction between fasting insulin and gender." (PMID 35585213, 2022). "Furthermore, phycocyanin can significantly reverse the decreased AKT signaling of diabetes mellitus mice and insulin-resistant SMMC-7721 cells." (PMID 37430932, 2022). "About 30% already received insulin prescriptions during the first years after diabetes diagnosis." (PMID 35933524, 2022). "In a pooled patient-level cohort of the PARADIGM-HF, ATMOSPHERE, and DAPA-HF trials, a previously derived simple risk model for stroke, consisting of three variables (history of prior stroke, insulin-treated diabetes, and plasma N-terminal pro-B-type natriuretic peptide level), was validated." (PMID 36017729, 2022).
diabetes (continued). "The novel coronavirus may affect insulin-producing pancreatic β cells (β-IPPs), being responsible for their apoptosis, decreased insulin levels, and increased insulin requirements in patients with COVID-19 leading to diabetic ketoacidosis and diabetes." (PMID 36406478, 2022). "The psychosocial outcomes assessed were not consistently associated with baseline participant characteristics (i.e., age, sex, diabetes duration, glycemic outcomes including percent time in range 70–180 mg/dL, percent time below range < 70 mg/dL, hemoglobin A1c, or insulin regimen)." (PMID 35853530, 2022). "Mn supplementation may protect mitochondria and islets from ROS by enhancing MnSOD activity and protecting against diabetes, but it was also suggested that Mn can inhibit glucose-stimulated insulin secretion in β-cells by impairing mitochondrial function." (PMID 36615774, 2022). "In addition, in vivo investigations, such as the oral glucose tolerance test, insulin sensitivity, gut sucrose content, gut perfusion, disaccharidase enzyme activity, and gut motility, are required to validate in vitro findings in Type 2 diabetes mellitus." (PMID 35270128, 2022). "This contributed to one's ability to manage their diabetes with insulin within four of the studies." (PMID 35983585, 2022). "The effects of insulin on blood glucose slowly dissipated after 1 h in all three mouse models of diabetes, which may be explained by the mutual binding cooperativity of IR-A62 and insulin." (PMID 35478209, 2022). "Defective insulin secretion is observed early in the development of diabetes." (PMID 35963866, 2022). "The ideal model for diabetes care would include the initial appointment and education session to be delivered in person with subsequent reviews via telephone consultations with the exception of commencement of insulin." (PMID 36514010, 2022). "The development of diabetes involves alterations in insulin-sensitive tissues." (PMID 36057662, 2022). "There are two primary forms of diabetes: type 1 diabetes (T1D), an autoimmune disease that occurs most often in children and adolescents, and T2D due to the body’s failure to respond adequately to insulin triggered by the pancreas." (PMID 35627115, 2022). "Insulin dependent models of diabetes exhibited hearts resistant toischemic/reperfusion insult." (PMID 39076631, 2022). "Several studies analysed the link between DISH and diabetes, and a possible pathogenetic mechanism might be that the high levels of insulin or insulin-like growth factors stimulate new bone formation." (PMID 36057932, 2022). "In the present patient, a delayed C-peptide secretary mode indicated impaired insulin secretion, so we speculated that direct islet injury might be an important reason for her diabetes." (PMID 35462530, 2022). "Rapid advances in the field of diabetes technology have led to the development of automated insulin delivery systems (AIDs), which combine an insulin pump and a dosing algorithm that dynamically controls the insulin infusion rate based on continuous glucose monitoring." (PMID 36147573, 2022). "T1DM is the form of diabetes mellitus which might exist as a result of the autoimmune destruction of the pancreatic beta-cells that produce insulin." (PMID 35356248, 2022). "Furthermore, HbA1c levels dependon diabetes history, medication regimes and short/long-term insulin dosage." (PMID 33765898, 2022). "In this context, results from the MIG (Metformin in Gestational Diabetes) trial and other studies suggest that its use in pregnancy is save and has some advantages over insulin (especially being weight neutral and without risk of hypoglycemia)." (PMID 35663318, 2022). "Insulin is still one of the most commonly prescribed medications for diabetes mellitus." (PMID 36404830, 2022).
diabetes (continued). "However, in the case of diabetes mellitus (DM), the body either cannot produce insulin or has resistance to it, so an external source of insulin needs to be used daily and is usually injected subcutaneously to treat T1DM or the advanced cases of T2DM." (PMID 36654645, 2022). "Diabetes is a condition marked by the insufficient or ineffective use of insulin." (PMID 36072265, 2022). "Metformin and Nifedipine (17.4%); Spironolactone Tab and Hydrochlorothiazide (HCT) (13.2%); Glimepiride and Enalapril (9.3%); and Insulin and Nifedipine (8.9%) were the most often utilized medications for the management of diabetes complications among the patients in the study area." (PMID 36419111, 2022). "The the methanol extract of Vigna radiata seeds also moderated lipid profiles, AST, ALT and glycated hemoglobin while restoring liver glycogen and insulin levels in diabetic mice, suggesting its potential advantages in reducing some of the consequences of diabetes." (PMID 36559668, 2022). "Diabetes occurs in two main types, type 1 and type 2, wherein those patients with type 1 diabetes produce no insulin whatsoever and those with type 2 diabetes respond to insulin inefficiently, if at all." (PMID 35711466, 2022). "In addition to the insulin signaling, Mg is also known to influence systemic inflammation, antioxidant parameters, and lipid profile in diabetes patients." (PMID 36249983, 2022). "Related to diabetes, it has been shown that memory deficits induced by chronic restraint stress are related to an impaired insulin signaling in mice, that is rescued by intranasal insulin treatment." (PMID 35958117, 2022). "Furthermore, metabolic effects, such as the lowering of hemoglobin A1c (HbA1c) in patients with ischemic heart disease and diabetes, or the improvement of insulin secretion and β-cell survival in diabetic mice, have already been described." (PMID 36233271, 2022). "Counsel patients about effects of exercise on insulin-requiring diabetes." (PMID 36589850, 2022). "Hyperglycemia can occur because of the inability of the pancreatic beta cells to secrete insulin or as may arise from insulin resistance and variable degrees of inadequate insulin secretion resulting in diabetes and related comorbidities." (PMID 36303652, 2022). "Furthermore, diabetes patients were more prone to have sleep disturbances, probably owing to hyperglycemia and altered insulin homeostasis." (PMID 36684994, 2022). "However, long-term in vivo studies and the characterization of genomic and epigenetic patterns of insulin-producing β-MSCs are needed to prove safety, stability, and potential for diabetes therapy." (PMID 35883121, 2022). "For example, upregulation of adipocyte SWELL1 protein expression using a small molecule approach (SN-401) activates SWELL1-dependent insulin signaling in adipocytes and improves systemic insulin sensitivity and tissue glucose uptake in mice with obesity and diabetes." (PMID 36483678, 2022). "Only 6% (n = 3) of patients in the OAH group, assumed that hypoglycaemic events during hospitalization occurred due to diabetes self-management (insulin dose calculation and insulin administration) versus 56% in the insulin group (n = 28) who also shared that belief (p<0.001)." (PMID 35482748, 2022). "The top 20 KEGG pathways of MLF targets include the PI3K- Akt signaling pathway (hsa04151), lipid and atherosclerosis (hsa05417), the AGE-RAGE signaling pathway in diabetic complications (hsa04933), insulin resistance (hsa04931), and type 2 diabetes mellitus (hsa04930)." (PMID 36278175, 2022). "Besides these, long-term apelin administration significantly improves pancreatic islet mass and insulin level in diabetes." (PMID 35355561, 2022). "Rutin improves the glycemic status in diabetes by decreasing small intestinal carbohydrate absorption, inhibiting tissue gluconeogenesis, increasing tissue glucose uptake, stimulating insulin secretion from β-cells, and protecting islets of Langerhans degeneration." (PMID 35847621, 2022).